ANGPT2 (angiopoietin 2)
Diseases named in the same sentence as ANGPT2 in open-access papers (continued):
Sharing a sentence is not in itself a finding about the gene and the disease.
Sepsis (continued). "Angiopoietin-2 was, furthermore, evaluated as a biomarker for sepsis and its sequelae." (PMID 34910264, 2021). "Furthermore, plasma angiopoietin-2 levels were significantly higher in both sepsis patients with more organ failures and those who died in the hospital." (PMID 33541396, 2021). "In the setting of sepsis, angiopoietin-2 is released into the circulation where it may have autocrine effects that include disruption of the endothelial barrier and increased microvascular permeability." (PMID 33541396, 2021). "Thus, angiopoietin 2 is considered as the common factor in the pathogenesis of CAC and sepsis-associated DIC." (PMID 33430431, 2021). "In the murine model of shock/sepsis-induced ARDS, mice deficient for PD1 or PDL1 manifested decreased BAL protein extravasation in response to injurious stimuli; suppressed barrier dysfunction was linked to the decreased Angpt2 production by endothelium." (PMID 33804896, 2021). "In the comparison of sepsis and septic shock, the number of biomarkers of endothelial dysfunction independently associated with septic shock dropped to four (SDC1, MR‐ProADM, THBD and ANGPT2)." (PMID 32073224, 2020). "Increased endothelial paracellular gap formation induced by serum obtained from sepsis patients could be fully neutralized by blocking angiopoietin-2." (PMID 30975180, 2019). "In addition, administration of an angiopoietin-2 inhibitor was found to protect endothelial integrity, reduce pulmonary vascular leakage, and improve survival in experimental sepsis models." (PMID 30975180, 2019). "Sepsis-induced alteration in angiogenic gene expression can be time-dependent and therefore it is possible that either downregulation or upregulation of Angpt2, Vagfα, and Flt1 was more robust at other time points." (PMID 25959381, 2015). "Furthermore, treatments targeted in animal models of sepsis to block angiopoietin-2, or enhance angiopoietin-1 have been shown to be protective." (PMID 26492036, 2015). "Angpt2 might therefore explain the regularly observed sepsis-like clinical picture of ALF patients and also serve as a marker of impending multiple organ failure." (PMID 22973230, 2012). "Angiopoietin-2 (ANGPT2) has been implicated in pulmonary vascular leak syndromes including ALI and sepsis in both animal and human studies, while recently, two ANGPT2 SNPs (rs2442598 and rs1868554) were found to be strongly associated with the development of ALI in patients with major trauma." (PMID 23369517, 2012). "CATK activity determined whether excess full-length ANGPT2 improves or exacerbates sepsis outcomes." (PMID 40029709, 2025). "We show that in sepsis patients, ageing was associated with a striking decrease of all measured endothelial cell activation markers (soluble E-selectin, soluble ICAM-1, fractalkine), an increase in angiopoietin-1 concentrations and a decrease of the angiopoietin-2/1 ratio." (PMID 36514130, 2022). "Thus, plasma angiopoietin-2 levels may serve as an additional biomarker for severe sepsis and septic shock." (PMID 36874368, 2022). "For instance, elevated levels of Angpt2 and VEGF, which play a role in signal transduction by endothelial-restricted receptor kinases Tie2 and VEGFR2 (discussed in more detail later), have both been associated with more severe disease progression and worsened clinical outcomes in sepsis patients." (PMID 35634305, 2022). "Moreover, when the expression of endogenous antagonist angiopoietin-2 (Ang-2) is increased, it displaces ang-1 from the endothelium-stabilizing receptor Tie2 in sepsis, inducing heightened heparanase expression, thus stimulating pathogenic sheddase of the endothelial glycocalyx." (PMID 36613805, 2022). "Finally, as this was an observational study, no conclusions about a causal role for angiopoietin-2 in the pathogenesis of sepsis-induced AKI can be made." (PMID 33541396, 2021).
Sepsis (continued). "Although the local presence of angiopoietin 2 at the portal of entry may be beneficial as a way of washing out the invasive pathogen, the target of sepsis-related research would be counter-measures by which a prolonged elevated level of circulating angiopoietin 2 might be brought into balance." (PMID 30134544, 2018). "Emerging biomarkers, such as histones and angiopoietin-2 (Ang-2), have great potential in the diagnosis of DIC, especially in sepsis." (PMID 39958822, 2025). "Genetic- or antibody-mediated reduction of ANGPT2, as well as the administration of TIE2 activating agents, confer vascular protection and reduced mortality in experimental models of sepsis." (PMID 35740360, 2022). "In contrast to angiopoietin-2, plasma angiopoietin-1 levels were significantly reduced in children with septic shock compared with those with critical SIRS and sepsis." (PMID 36874368, 2022). "Plasma angiopoietin-2 levels and angiopoietin-2/1 ratio were correlated with the SOFA score and showed a good indicator of 28-day mortality in sepsis patients." (PMID 36874368, 2022). "Not surprisingly, enhanced expression levels of significant angiogenic biomarkers including angiopoietin-2 and VEGF-A have been demonstrated in septic shock, while the role of VEZF1 in sepsis is rarely reported." (PMID 34804111, 2021). "The present results describe a potentially new proteolytic mechanism arising from inflammation to transform ANGPT2 into a Tie2 antagonist and a new action of a clinical-stage compound to mitigate adverse outcomes of sepsis in a CATK- and ANGPT2-dependent fashion." (PMID 40029709, 2025). "Moreover, sepsis patients also presented notably increased histone H3, myeloperoxidase (MPO), angiopoietin-2 and endocan levels in the blood, and such increase was positively correlated with the number of EVs." (PMID 37559007, 2023). "A limitation of the current study was the lack of APACHE-II scores and procalcitonin levels of the control individuals thus the additional analysis to identify the optimal cutoff of angiopoietin-2 for discriminating sepsis has not been performed." (PMID 36874368, 2022). "Survivors from sepsis had higher angiopoietin-1 levels and lower angiopoietin-2 levels compared with individuals without infection." (PMID 36874368, 2022). "We previously reported that elevation in endothelial biomarkers ANGPT2/ANGPT1 ratio, VCAM1, and vWF distinguished children with ARDS due to indirect (e.g., extrapulmonary sepsis or trauma, shock, transfusion, pancreatitis) compared to direct (e.g., pneumonia, aspiration, drowning) lung injury." (PMID 35913450, 2022). "In addition, angiopoietin-2 has been shown to act as a partial TIE-2 agonist and contribute to endothelial cell survival, and that is therefore an important mediator in sepsis." (PMID 36874368, 2022). "Sepsis predictably increased serum concentration of acute, proinflammatory cytokines, such as IL-6, as well as markers of endothelial dysfunction markers (ICAM-1 and angiopoietin 2)." (PMID 35286340, 2022). "Plasma levels of angiopoietin-2, endocan, sVE-cadherin, and syndecan-1 were significantly higher in sepsis patients with severe AKI compared to those without severe AKI." (PMID 33541396, 2021). "In sepsis, angiopoietin-2 levels correlated with severity of organ failure in critically ill children, while non-survivors showed higher angiopoietin-2 concentration." (PMID 34910264, 2021). "Indeed, both endocan and angiopoietin-2 are endothelial-specific biomarkers which increase during sepsis, worsening into multiple organ dysfunction syndrome (MODS), and decrease when sepsis improves." (PMID 30367649, 2018). "Angiopoietin-2 and the ratio of angiopoietin-2/angiopoietin-1 were higher in hypothermic patients on day 2 compared to nonhypothermic patients with sepsis." (PMID 27737683, 2016).
Sepsis (continued). "Similarly, a study investigated serum angiopoietin-2 levels of patients with sepsis and those with severe sepsis and septic shock and showed higher angiopoietin-2 levels in severe sepsis and septic shock, compared with those with sepsis without complications." (PMID 36874368, 2022). "In addition, elevated plasma levels of angiopoietin-2 and TIE-2 receptors have been observed in adults with congestive heart failure and in adults with acute sepsis-induced lung injury, and this elevation contributes to endothelial damage in vascular endothelial cells." (PMID 36874368, 2022). "Next, we sought to determine whether plasma angiopoietin-2 levels were associated with severe AKI in both pulmonary and non-pulmonary sepsis." (PMID 33541396, 2021). "The serum levels of three mediators, VEGF (55 ± 21 pg/ml vs. 17 ± 3.2 pg/ml, P = 0.03), angiopoietin-2 (62,379 ± 6,020 pg/ml vs. 5,892 ± 510 pg/ml, P < 0.0001), and SDF-1 (4,223 ± 360 pg/ml vs. 2,143 ± 117 pg/ml, P < 0.0001) were significantly higher in patients with sepsis than in healthy controls." (PMID 21396100, 2011). "Furthermore, sepsis patients with severe AKI had higher plasma angiopoietin-2 levels regardless of whether sepsis was pulmonary or non-pulmonary." (PMID 33541396, 2021).
endothelial dysfunction (61 papers, 2014 to 2026). In vascular diseases, endothelial dysfunction is a systemic pathological state of the endothelium (the inner lining of blood vessels) and can be broadly defined as an imbalance between vasodilating and vasoconstricting substances produced by (or acting on) the endothelium. "Angiopoietin-2, a pro-inflammatory cytokine, and cleaved thrombomodulin is elevated in plasma in severe COVID-19 and has been linked to endothelial dysfunction and hypercoagulability." (PMID 41620635, 2026). "Among them, angiopoietin-2 (Ang-2) has gained particular interest due to its association with endothelial dysfunction and increased vascular permeability." (PMID 40731746, 2025). "Endothelial dysfunction is also associated with endothelial expression of many prothrombotic molecules and receptors, including P-selectins, angiopoietin-2, and endothelin-1." (PMID 36034557, 2022). "Serum concentrations of markers associated with endothelial dysfunction (angiopoietin-2 and sFlt-1) were highest in SAP." (PMID 36294481, 2022). "Increased angiopoietin-2(ANGPT2) serum levels, an endothelial dysfunction and injury biomarker, has been demonstrated to be associated not only with endothelial dysfunction, but also with DKD." (PMID 35468852, 2022). "The delayed increase in angiopoietin-2 following CPB implies that angiopoietin-mediated endothelial barrier dysfunction happens secondary to early CPB-associated endothelial dysfunction and microvascular alterations." (PMID 30975180, 2019). "Angiopoietin-2 (Ang-2), associated with endothelial dysfunction and vascular leakage in acute states, has been recently proposed as a marker of severity in AP." (PMID 27929426, 2016). "In another adult study increased plasma angiopoietin 2, a marker of endothelial dysfunction and vascular permeability, was associated with increased mortality and fewer ventilator-free-days." (PMID 26652251, 2015). "Angpt2 was considered as a proangiogenic factor that could be responsible for endothelial dysfunction and increased risk for vascular disorders and functioned as a biomarker to predict the life expectancy of peripheral arterial disease patients." (PMID 37533068, 2023). "TIE1 and TIE2 are receptor tyrosine kinases that govern endothelial cell survival and angiogenesis, while ANGPT2 is pivotal in mediating endothelial dysfunction and vascular permeability." (PMID 40506916, 2025). "Two that focus on endothelial dysfunction are ANGPT2 and vascular endothelial-Cadherin, both found in elevated levels in the CSF." (PMID 41008364, 2025). "Descriptive profiling of these biomarkers, including CXCL9, angiopoietin-2, and soluble E-selectin, suggests their potential value in understanding endothelial dysfunction, macrophage activation, and immune dysregulation in MIS-C." (PMID 40430232, 2025). "Plasma levels of the markers of endothelial dysfunction angiopoietin-2, syndecan-1, and Vascular cell adhesion molecule 1 (VCAM-1) show a moderate positive correlation with PD-1 expression in CD4+ T-cells (shown for TP2)." (PMID 40595657, 2025). "ABTAA’s unique ability to bind and cluster ANGPT2 into a potent TIE2 activator helps to prevent endothelial dysfunction, tubular injury, and tubulointerstitial fibrosis in experimental CKD." (PMID 40952790, 2025). "ANGPT2, one of the proposed miR-1 targets, is a well-known mediator of endothelial dysfunction and cell death in ALI." (PMID 37737266, 2023). "They found lower levels of markers of endothelial dysfunction (angiopoietin 2:1 ratio) and inflammation (soluble tumor necrosis factor receptor 1) in COVID-19 compared to patients without COVID-19." (PMID 37686001, 2023). "Among those analyzed in this study, angiopoietin-2 (Ang-2), a modulator of endothelial dysfunction, earns a special significance." (PMID 37373181, 2023).
endothelial dysfunction (continued). "Ischemia-induced endothelial dysfunction was illustrated by several other genes and pathways, for instance dysregulation of lipidic pathways and upregulation of Angpt2, which was included in the BBB dysfunction module." (PMID 37691115, 2023). "While the ANGPT2 inhibition of normal ANGPT1-TIE2 signaling probably has a role in endothelial dysfunction and coagulopathy, it was also shown in vitro that ANGPT2, and to a lower extent ANGPT1, can bind and inhibit the function of thrombomodulin (TM)." (PMID 35740360, 2022). "In other words, endothelial dysfunction and damage is followed by endothelial expression of prothrombotic molecules and receptors, such as P-selectins, angiopoietin-2 and endothelin-1, which actively contribute to thrombosis." (PMID 36295093, 2022). "The analysis of differentially expressed genes showed that some genes associated with endothelial dysfunction were significantly upregulated, such as CD36, EDN1, ANGPT2 and so on." (PMID 36091033, 2022). "In contrast, angiopoietin 2:1 (Ang-2:1 ratio) and soluble tumor necrosis factor receptor 1 (sTNFR-1), markers of endothelial dysfunction and inflammation, were significantly lower in COVID-19 (p < 0.002)." (PMID 33874973, 2021). "Patients with persistent HRF displayed higher biomarkers of inflammation (interleukin-6, interleukin-8) and endothelial dysfunction (angiopoietin-2) than resolving HRF after adjustment." (PMID 34526076, 2021). "In conclusion, the present study demonstrates that among four plasma biomarkers of endothelial dysfunction and injury, the best performing biomarker independently associated with severe AKI is angiopoietin-2." (PMID 33541396, 2021). "Our previous study has found that increased angiopoietin-2 (Ang-2), an indicator of endothelial dysfunction, was related to elevated HIF-α in mouse kidneys." (PMID 34268320, 2021). "Plasma endothelial dysfunction and injury biomarkers, including angiopoietin-2, soluble vascular endothelial cadherin (sVE-cadherin), endocan and syndecan-1, were measured at study enrollment." (PMID 33541396, 2021). "BTP measured on day 1 following admission as well as the maximum concentrations recorded on the first two days of hospital stay were also positively correlated with the studied markers of endothelial dysfunction: angiopoietin 2 and sFlt-1." (PMID 31940861, 2020). "On day 1 following patients’ admission, we have found significant positive correlations between serum BTP and the markers of endothelial dysfunction or injury, i.e., serum angiopoietin-2 and sFlt-1." (PMID 31940861, 2020). "These abnormalities correlated with both inflammation (as reflected by C-reactive protein concentrations) and endothelial dysfunction (as reflected by the concentrations of angiopoietin-2 and sFlt-1)." (PMID 28368336, 2017). "Recently, angiopoietin-2 and soluble fms-like tyrosine kinase 1 (sFlt-1) were proposed as markers of endothelial dysfunction in acute states." (PMID 28368336, 2017). "Angiopoietin-2 (Ang-2), a mediator of endothelial dysfunction, was also highly elevated (mean: 6426 pg/mL, CV = 104.0%), reinforcing the hypothesis of systemic vascular inflammation and capillary leakage in MIS-C." (PMID 40430232, 2025). "Elevated levels of complement-related markers such as von Willebrand factor, thrombomodulin, and angiopoietin-2 are frequently observed in patients with severe COVID-19, underscoring the link between complement activation, endothelial dysfunction, and thrombotic complications." (PMID 41458994, 2025). "Various markers of endothelial injury have been investigated in CAR-T cell recipients, including markers of complement activation, such as soluble C5b-9, endothelial dysfunction (angiopoietin-2, VCAM1, ICAM-1), inflammation, and thrombosis (von Willebrand antigen, ADAMTS13, thrombomodulin)." (PMID 40940973, 2025).